NEU1 (neuraminidase 1)
Diseases named in the same sentence as NEU1 in open-access papers (continued):
Sharing a sentence is not in itself a finding about the gene and the disease.
atherosclerosis (continued). "Lipopolysaccharide (LPS), NEU1, and IL-1β act in a positive feedback loop as enhancers of inflammation in monocytes/macrophages and may therefore promote atherosclerosis and plaque instability." (PMID 34869700, 2021). "The recent study discovered a new Neu1-dependent pathway that contributes to atherosclerosis." (PMID 34070542, 2021). "PI3Kγ is involved in neuraminidase-1 (Neu-1) signaling, which governs atherosclerosis development." (PMID 33381504, 2020). "Thus, in addition to the adverse role of NEU1 in monocytic cells in atherosclerosis, NEU1 promotes higher and prolonged inflammation in monocytic cells in the infarcted heart after reperfusion and thereby contributes to heart failure." (PMID 32975669, 2020). "This has been further strengthened by the recent demonstration of a positive feedback loop between IL-1β, LPS and NEU1 in monocytes and macrophages that may promote atherosclerosis by enhancing a pro-inflammatory state." (PMID 30498996, 2019). "In addition, NEU1 can potentiate inflammation in atherosclerosis." (PMID 39596031, 2024). "Last, as these compounds appear to be effective in inhibiting membrane NEU-1 in vitro, they could be used in in vivo models to down-regulate this protein involved in several diseases such as atherosclerosis, thrombosis, insulin resistance, non-alcoholic steatohepatitis, and cancer." (PMID 33920466, 2021). "We conclude that NEU1 may represent a promising target for managing atherosclerosis." (PMID 31521172, 2019). "EDP activities impact the course of atherosclerosis through regulating the levels of the sialylation of CD36, a process largely governed by the ERC and its catalytic subunit, NEU1, to modulate oxLDL uptake in these cells." (PMID 39194692, 2024). "The sialidase genes NEU1 and NEU3 were found upregulated in the cardiovascular disease models, whereas disrupting NEU1 and NEU3 in mice attenuates atherosclerosis, cardiac hypertrophy, and cardiac fibrosis." (PMID 39596031, 2024). "In cardiovascular disease models, both NEU1 and NEU3 are upregulated, and genetic disruption of NEU1 or NEU3 in mice, or treatment of mice with sialidase inhibitors, attenuate atherosclerosis, cardiac hypertrophy, or cardiac fibrosis." (PMID 36613682, 2022). "Mechanistically, PI3Kγ participates to neuraminidase-1 (Neu-1) signaling downstream leukocyte elastin receptor complex (ERC) and crucially governs monocyte migration, ROS production and the ensuing atherosclerosis development in response to elastokines." (PMID 26321955, 2015). "With reference to the potent effects of NEU1 inhibition regarding atherosclerosis, CAD and MI damage, NEU1 inhibition is an exciting therapeutic approach which can help to improve important risk factors (atherosclerosis, CAD), fatal events (MI, MI/IR damage) and CM itself." (PMID 36009856, 2022). "Human NEU-1, the ERC catalytic subunit, is known, after activation of its sialidase activity by EDP, to be involved in several pathophysiological contexts as cancers, diabetes, atherosclerosis, and nonalcoholic steatohepatitis." (PMID 33920466, 2021). "In summary, NEU1 down-regulation could reduce non-HDL cholesterol, inhibit leukocyte transmigration and attenuate atherosclerosis in Apoe knockout mice." (PMID 31521172, 2019).
type I sialidosis (18 papers, 2014 to 2026). "To date, over 30 NEU1 mutations have been identified as causes of sialidosis type I, with missense mutations being the most prevalent, while exon duplications or small deletions are less common." (PMID 39605025, 2024). "Sialidosis type 1 (ST-1) is a rare autosomal recessive disorder caused by mutation in the NEU1 gene." (PMID 39350194, 2024). "The same study also used human WG544 or 1140F01 type 1 sialidosis fibroblast cell lines, genetically deficient in Neu-1." (PMID 37174732, 2023). "This pharmacologic, chaperone-mediated therapy has been regarded as a promising approach for other NEU1 mutations found in patients with type I sialidosis." (PMID 35847014, 2022). "Seven patients with sialidosis type I (mutations in NEU1) and one with galactosialidosis (mutations in CTSA) were included." (PMID 32753397, 2021). "So far homozygous or compound heterozygous missense, frameshift, truncating mutations as well as duplications and deletions of the NEU1 gene have been reported in patients with sialidosis type 1." (PMID 34992946, 2021). "So far, more than 40 mutations within the NEU1 gene have been identified in patients with sialidosis types I and II." (PMID 29693572, 2018). "The new mouse model ubiquitously expresses a NEU1 variant, which has a V54M amino acid substitution found in an adult patient with type I sialidosis." (PMID 29693572, 2018). "The genetic analysis detected a new NEU1 mutation, which caused type I sialidosis." (PMID 39298726, 2023). "Injection of aged mutant mice with AAV-PPCA caused improvement of symptoms in the disease phenotype, hence suggesting that some NEU1 mutations associated with type I sialidosis may respond to PPCA-chaperone-mediated gene therapy." (PMID 29693572, 2018). "Researchers believe that the treatment may be useful for other NEU1 mutations, particularly those in patients with type I sialidosis." (PMID 29693572, 2018). "More recently, a deletion of NEU1 exon 2 was reported in a patient with type 1 sialidosis, as well as a heterozygous 27.5 kb deletion involving the whole coding exons of NEU1 in a girl with reduced visual acuity." (PMID 36009380, 2022). "As expected for other LSDs, the residual NEU1 activity in sialidosis type I patients ranges from 1% to 5% of normal enzyme levels." (PMID 32143456, 2020). "We have reported the clinical, neuroradiological, ophthalmological, and electrophysiological course of four unrelated patients affected by type 1 sialidosis, bearing compound heterozygosity of NEU1, and described the long-term follow-up of their disease." (PMID 32752208, 2020). "Thus they may represent new, putative pathological mutations resulting in sialidosis type I. The in silico approach used in this study has enabled the identification of previously unknown NEU1 functional alleles that are widespread in the population and could be tested in future functional studies." (PMID 25153125, 2014). "Future studies on a larger number of patients with sialidosis type I may shed more light on how NEU1 and PPCA regulate each other and influence their reciprocal activities." (PMID 32143456, 2020). "Interestingly, dietary supplementation of betaine, a natural amino acid derivative, in mouse models with residual NEU1 activity mimicking type I sialidosis, increased the levels of mutant NEU1 and resolved the oligosacchariduria." (PMID 32143456, 2020). "Recent studies have reported that atypical cases of type I sialidosis exhibited myoclonus without visual symptoms and no measurable NEU1 activity." (PMID 35847014, 2022).
galactosialidosis (16 papers, 2012 to 2025). A lysosomal storage disease characterized by coarse facial features, macular ''cherry red spot'', and dysostosis multiplex. "This is particularly important, given that Neu1 deficiency is associated with increased lysosomal exocytosis and onset of the neurodegenerative lysosomal storage diseases sialidosis and galactosialidosis." (PMID 31481471, 2020). "Although the CathA−/− knockout mouse model presents phenotypes similar to human patients with galactosialidosis, severe symptoms arising due to the secondary deficiency of Neu1 and β-Gal prevent the use of this mouse model for behavioral analysis." (PMID 28133419, 2017). "Genetic mutations in the CathA gene are characterized by the occurrence of the lysosomal storage disorder galactosialidosis, which involves a secondary deficiency of Neu1 and β-Gal." (PMID 28133419, 2017). "In contrast, in MPS IIIC mouse brains, NEU1 was deficient but GLB1 was increased, and GALNS was only slightly reduced, as in the tissues of galactosialidosis CathAS190A-neo mice, consistent with high stability of mouse GLB1 and GALNS enzymes in the lysosome." (PMID 40540388, 2025). "Functionally, lysosomal CTSA is part of a multienzyme complex, and it is required to stabilize β-galactosidase and activate neuraminidase 1 and mutations in the CTSA gene have been linked with galactosialidosis." (PMID 38775843, 2024). "In our galactosialidosis model, CathAS190A-Neo mice, the kidneys are normal, suggesting that just 10% of the residual NEU1 activity is sufficient to protect mice from a severe kidney damage." (PMID 37698928, 2023). "Given that CathAS190-Neo mice (galactosialidosis model), which have approximately 90% reduction in tissue NEU1 activity, develop type 2 diabetes, we sought to document if hyperglycemia was also observed in Neu1-null mice." (PMID 37698928, 2023). "Thus, mutation analysis of the patient’s CTSA gene and biochemical assessment of the cathepsin A, β-galactosidase, and neuraminidase-1 activities in cultured fibroblasts should be performed to support the diagnosis of early infantile galactosialidosis." (PMID 31484286, 2019). "In addition, the genetic deficiency of CTSA results in the secondary deficiencies of NEU1 and GLB1, and causes the lysosomal storage disorder (LSD) galactosialidosis (GS OMIM #256540)." (PMID 30088207, 2018). "The gel-filtration profiles of NEU1 and GLB1 activities were compared for the WT, HgsnatP304L, and galactosialidosis CathAS190A-Neo mice." (PMID 40540388, 2025).
Alzheimer disease (12 papers, 2014 to 2025). A progressive, neurodegenerative disease characterized by loss of function and death of nerve cells in several areas of the brain leading to loss of cognitive function such as memory and language. "NEU1 is strongly implicated in Alzheimer’s disease (AD) pathogenesis, where it regulates amyloid precursor protein (APP) metabolism through desialylation." (PMID 39194692, 2024). "The loss of function of the lysosomal sialidase NEU1 leads to an Alzheimer's disease (AD)‐like process in mice due to the accumulation of hypersialylated amyloid precursor protein in lysosomes and the extracellular release of amyloid β peptides." (PMID 35128728, 2022). "Deficiency of the lysosomal sialidase Neu1 was found to lead to the spontaneous occurrence of an Alzheimer's disease-like amyloidogenic process in mice." (PMID 25211026, 2014). "However, the fact that NEU1 has been linked to the pathology of Alzheimer’s disease, which is rapidly growing worldwide, makes it more relevant to be studied and explored." (PMID 35847014, 2022). "Additionally, in the hippocampal region of the Neu1-null mice, recent studies have suggested a link between NEU1 deficiency-exacerbated lysosomal exocytosis and the spontaneous occurrence of Alzheimer’s disease (AD)-like amyloidogenic process." (PMID 29693572, 2018). "For example, numerous recent studies have demonstrated a therapeutic role of NEU1 in Alzheimer’s disease (AD), which is the most common type of neurodegenerative disease causing dementia [1213]." (PMID 35847014, 2022). "The brains of Neu1−/− mouse models were shown to exhibit features of Alzheimer’s disease (AD)-related pathology and phenotypes, including increased β-amyloid plaque formation and secretion." (PMID 33922276, 2021).
colon cancer (12 papers, 2012 to 2024). "NEU1 played a crucial role in regulation of integrin β4-mediated signaling through desialylation of integrin β4, and suppressed metastasis of human colon cancer cells." (PMID 32164705, 2020). "NEU1 was reported to suppress metastasis both in vitro and in vivo in human colon cancer, however in ovarian cancer, knock down of NEU1 inhibited the proliferation, apoptosis, and invasion of tumor cells." (PMID 27602751, 2016). "Neu1 plays an important role in regulating invasion and metastasis in different cancer types including human colon cancer and is reported to be a direct target of miR-125b." (PMID 25184537, 2014). "A target gene of rs4779584 is a growth-associated gene NEU1 [MIM:608272] (growth gene expression association ), which has been reported to contribute to the suppression of metastasis of human colon cancer." (PMID 22346769, 2012). "Furthermore, NEU1 overexpression in colon cancer HT-29 cells decreased cell migration and cancer cell invasion." (PMID 39194692, 2024). "NEU1 overexpression has been described to reduce metastases in vivo and to suppress migration, invasion and adhesion in vitro, yet its silencing results in the opposite effects in colon cancer." (PMID 35354905, 2022). "In human colon cancer, NEU1 expression was negatively correlated with metastasis." (PMID 32164705, 2020). "NEU1 has specifically been suggested to suppress metastasis in human colon cancer cells." (PMID 29547645, 2018). "NEU4 was down-regulated in all EMT-induced cancer stem-like cells colon cancer cell lines DLD1, HT29 and LS174T, but not NEU1, NEU2 and NEU3." (PMID 30700826, 2019).
ovarian carcinoma (12 papers, 2014 to 2025). A malignant neoplasm originating from the surface ovarian epithelium. "The siRNA of NEU1 in human ovarian cancer effectively inhibited proliferation, apoptosis, and invasion of cells by targeting lysosome and oxidative phosphorylation signaling." (PMID 37601653, 2023). "In pancreatic cancer, enhanced NEU1 expression promotes cancer progression and metastases; in ovarian cancer, NEU1 siRNA knockdown inhibits cell invasion." (PMID 35354905, 2022). "Fewer studies also elaborate on the role of neuraminidases in ovarian cancer, one being where higher expression of NEU1 in ovarian cancer tissues of patients in comparison to adjacent normal tissues was noted." (PMID 36547200, 2022). "Implication of EDP and Neu-1 in other cancer types has also been shown: Neu-1 is involved in the development of hepatocellular carcinoma and ovarian cancer." (PMID 32351895, 2020). "We also observed that OP, anti-Neu1 antibody and specific inhibitor MMP-9i treatment of A2780 ovarian cancer cell line blocked Neu1 activity associated with EGF-stimulation of live A2780 cells." (PMID 26932374, 2014). "The inhibition of NEU-1 expression decreases the cell proliferation, migration and invasion and cancer metastasis of several ovarian cancer cells, thereby suggesting that NEU-1 could be also a key target for the treatment of ovarian cancers." (PMID 36230790, 2022). "In addition, the effects of siRNAs which are directed against NEU-1 have been studied in ovarian cancer proliferation, apoptosis and invasion." (PMID 36230790, 2022). "They further elucidate the role of NEU1 siRNA, which via targeting lysosome and oxidative phosphorylation signaling, effectively inhibits the proliferation, apoptosis, and invasion of human ovarian cancer cells suggesting NEU1 can be targeted for the treatment of ovarian cancer." (PMID 36547200, 2022). "NEU-1 is highly expressed in ovarian cancer cells in comparison with adjacent healthy tissues." (PMID 36230790, 2022). "In ovarian cancer, NEU1 siRNA inhibited cell proliferation, apoptosis, and invasion." (PMID 32164705, 2020). "Furthermore, NEU1 is overexpressed in ovarian cancer tissues compared with adjacent normal tissues." (PMID 37601653, 2023). "Collectively, these different signaling paradigms involved with EMT in ovarian cancer suggest that growth factor receptor glycosylation modification involving the receptor-signaling platform of a Neu1-MMP-9 crosstalk may in fact be the invisible link connecting the Snail-MMP-9 signaling axis." (PMID 26932374, 2014). "By screening 31 drugs with 110 targets, FNTA, HSPA5, NEU1, CCND1, CASP1, CASP3 were negatively correlated with ovarian cancer, and HMGCR, PLA2G4A, ITGAL, PTGS1, FNTB were positively correlated with ovarian cancer." (PMID 38651149, 2024). "Similarly, our observations that single gene knockouts of ALDOB, ADH1B, NEU1, and NT5E block the metabolic alterations during both transitions concur with previous studies that show suppression of ovarian cancer growth upon silencing these genes." (PMID 37876796, 2023). "Among them, FNTA, HSPA5, NEU1, CCND1, CASP1, CASP3 had a negative causal association with ovarian cancer development, and HMGCR, PLA2G4A, ITGAL, PTGS1, FNTB had a positive causal association with ovarian cancer development." (PMID 38651149, 2024). "In addition aspirin may inhibit several targets such as HSPA5, NEU1, CCND1, CASP1, CASP3, which are negatively correlated with ovarian cancer prognosis." (PMID 38651149, 2024). "Here, Neu1 might be an intermediate candidate connecting the Snail-MMP9 signaling axis in tumor neovascularization and in promoting the growth and invasiveness of human triple negative breast and ovarian cancers." (PMID 27029067, 2016). "Based on these observations, we propose that Neu1 might be an intermediate candidate connecting the Snail-MMP signaling axis in tumor neovascularization and in promoting the growth and spread of human ovarian cancer." (PMID 26932374, 2014).